CDKN2A (cyclin dependent kinase inhibitor 2A)
Diseases named in the same sentence as CDKN2A in open-access papers (continued):
Sharing a sentence is not in itself a finding about the gene and the disease.
tumor (continued). "The qRT-PCR results revealed that AXL (p = 0.0308), FAS (p = 0.0134), TNFRSF1B (p = 0.0250), and CDKN2A (p = 0.0224) mRNA expression were considerably greater in tumor tissues." (PMID 36186479, 2022). "As a tumor suppressor, CDKN2A is involved in B-cell differentiation, cell survival, and cell cycle progression." (PMID 35311137, 2022). "The differential analysis also confirmed the high expression of CD74, HLA-DRA, C7, CCL12, and CCR3 in CAFs from P-LN but lower expression of VIM, APOD, MMP11, TAGLN, and CDKN2A compared with that in the primary tumor." (PMID 36569924, 2022). "The variant rs3731198 is located in the CDKN2A/CDKN2B gene region, which is an important tumor suppressor gene involved in cell cycle regulation." (PMID 36233401, 2022). "Due to the high incidence of 9p21.3 deletions across tumor types, we performed a pan-cancer analysis and found CDKN2A deletion-positive tumors had worse survival following first-line immunotherapy treatment in multiple tumor types (HR = 1.4, P < 0.001)." (PMID 35739333, 2022). "The protein levels of CDKN2A in OS and tumor-adjacent tissues were detected by corresponding antibody and IgG (isotype) immunohistochemistry." (PMID 36263140, 2022). "These functional alterations were associated with changes in the expression of different tumour markers (CCND1, CDKN2A, etc.; determined by qPCR), which were modulated in a cell‐dependent manner in response of EIF4A3‐silencing." (PMID 36419260, 2022). "In the chemotherapy arm, early progression was associated with liver, adrenal gland or brain metastasis, or greater number of metastatic sites overall, higher SLD or tumor mutations in SMARCA, ASXL1 or CDKN2A (P < 0.05)." (PMID 35995953, 2022). "TMB (tumor mutation burden) and MSI (microsatellite instability) status are related to CDKN2A expression for the clinicopathological characteristics of tumor stage pathology grade." (PMID 35004697, 2021). "Cdkn2a deletion and Hedgehog and Hippo pathway activation have been observed in murine models of asbestos exposure well before tumour development." (PMID 34580349, 2021). "The Cdkn2a locus is one of the most studied tumor suppressor loci in the context of several cancer types." (PMID 33917623, 2021). "PD-L1 protein expression levels on both immune and tumor cells measured by IHC staining were decreased in the lo_lo group, especially in tumors with low (Q1) CDKN2A expression (left)." (PMID 34556668, 2021). "We observed that tumours with this deletion had a higher copy number burden compared with CDKN2A wild type patients, consistent with cell cycle dysregulation." (PMID 34580349, 2021). "Clonal homozygous deletion involving the region 9p21.3, which harbours the tumour suppressors cyclin-dependent kinase inhibitor 2A and B (CDKN2A/B) and methylthioadenosine phosphorylase (MTAP), was found in seven patients (32%)." (PMID 33741915, 2021). "We also identified 44 lost segments, which harbored tumor suppressors including CDKN2A (9p21.3), ADAM3A (8p11.22), and CFHR1/CFHR4 (1q31.3)." (PMID 34070941, 2021). "Our research targeted the analysis of CDKN2A expression in 33 tumors and clinical parameters, patient prognosis and tumor immunity roles." (PMID 35004697, 2021).
tumor (continued). "Similar to RB1, genes that scored as hits both in the Drosophila eye screen and cancer cell line screens had least hazard than any other group of genes in patients with low expression levels of CDKN2A (p16Ink4a) in tumor samples." (PMID 33591981, 2021). "In contrast, in the case of TSGs (i.e., CDKN2A, CTNNB1, and SPOP), MSCs were small and the differences between “mutation-tumor type” combinations are also small." (PMID 34424899, 2021). "Formation of colony was dramatically inhibited upon expression of FCN3 in a similar manner to that of CDKN2A, a well-established tumor suppressor gene." (PMID 33859174, 2021). "The CDKN2A expression level was significantly correlated with the tumor mutation burden (TMB) in 10 tumors, and the expression of CDKN2A was also correlated with MSI (microsatellite instability) in 10 tumors." (PMID 35004697, 2021). "CDKN2A has been shown to be silenced in many tumour types through promoter methylation of CDKN2A/P16 locus." (PMID 34439335, 2021). "CDKN2A expression levels, clinical parameters, patient prognosis and tumor immunity were investigated in 33 tumors." (PMID 35004697, 2021). "These proteins function as tumor suppressors, and homozygous deletion of CDKN2A/B can contribute to uncontrolled tumor cell proliferation." (PMID 33838014, 2021). "The skin metastasis sample showed a very similar pattern of alterations in driver genes as compared with the treated tumor, including the PIK3CA hotspot mutation, the amplifications in CCND1, EGFR, and FGFR3, and the deletions in CDK1B, CDKN2A, and CDKN2B." (PMID 34680239, 2021). "Genomic comparisons of these subtypes do not reveal mutually exclusive somatic alterations, with all harbouring, to some extent, the three most common tumour suppressors at 9p21.3 (CDKN2A), 3p21 (BAP1), or 22q (NF2)." (PMID 34067960, 2021). "For tumor immune cell infiltration, the results suggested that CDKN2A expression was positively related to CD8 T cells, NK activated cells and CD4 T activated cells but negatively related to memory resting CD4 T cells and resting CD4 T cells." (PMID 35004697, 2021). "The two kinds of proteins encoded by the CDKN2A/2B gene are the INK4 family member p16 (p16INK4a) and p14arf, which act as tumour suppressors by regulating the cell cycle." (PMID 34418317, 2021). "House and colleagues identified hypermethylation of CDKN2A in 40% of 48 patients with pNETs who underwent tumour resection." (PMID 34439335, 2021). "CDKN2A is a well-known tumor suppressor, which regulates cell cycle progression by inhibiting cyclinD-CDK4 and cyclinD-CDK6 complexes responsible for initiating the G1/S phase transition." (PMID 33845897, 2021). "In mice, mutations in CDKN2A gene, affecting either or both encoded proteins p16 and p19, or in CDKN1A, result in increased tumour development susceptibility." (PMID 33439271, 2021).
tumor (continued). "Deletion of CDKN2A was the most frequent event observed in our samples, detected in 71/118 tumours (60%), with 58 deletions (82%) predicted to be homozygous." (PMID 34580349, 2021). "CDKN2A, also known as cyclin-dependent kinase inhibitor 2A by binding to cyclin-dependent kinases (CDKs), acts as a tumor suppressor by blocking the cell cycle from G1 to S phase." (PMID 34336665, 2021). "Our finding of RB1 deletions in 34% of tumours with CDKN2A deletion makes responses to CDK4/CDK6 antagonists less likely and underpins our finding that the CDK4/CDK6 inhibitor Palbociclib had marginal effects on primary cell survival." (PMID 34580349, 2021). "Patients were classified according to their CDKN2A status (p16-low or p16-high), and differential expression analysis was performed independently for each tumor type." (PMID 33550279, 2021). "The tumor-suppressor products of CDKN2A/B, p15INK4b, and p16INK4a inhibit important CDKs, i.e., CDK4 and CDK6, essential for β-cell proliferation and regeneration." (PMID 34925466, 2021). "A recent study revealed that somatic tumor genomic profiles by FoundationOne® CDx showed a high prevalence of p16/CDKN2A alterations in MPNST, MFS, and UPS." (PMID 34461930, 2021). "Cdkn2a is one of the most intensively studied tumor suppressor loci, as several malignant tumors show abnormalities in the Cdkn2a sequence and expression status." (PMID 33917623, 2021). "The impact of CDKN2A on the prognostic value of tumor samples was analyzed and compared with that of normal samples." (PMID 35004697, 2021). "Loss of CDKN2A/CDKN2B genes in tumor Schwann cells first leads to development of premalignant, atypical neurofibromatosis neoplasms of uncertain biological potential (ANNUBP)." (PMID 33863389, 2021). "A prime example is MTAP, the rate limiting enzyme in the methionine salvage pathway, which is deleted in a variety of cancers along with the neighboring tumor suppressors CDKN2A and ARF." (PMID 34109280, 2021). "Genomic testing revealed increased tumor mutational burden and alterations in NF1, BRAF, CDKN2A/B, TERT." (PMID 34926265, 2021). "The tumor tissues were subjected to whole exome sequencing (WES) and four mutations with potential clinical significance were identified: CDKN2A deletion, CDK6 amplification, PIK3CA amplification, and KRAS G12V mutation." (PMID 34327143, 2021). "The treated tumor showed several CNVs in driver genes, including amplifications in MCL1, TERT, CCND1, AKT1, MYC, EGFR, and FGFR3; deletions in CDK1B, CDKN2A and CDKN2B; a PIK3CA hotspot mutation; and a high TMB." (PMID 34680239, 2021). "For tumor microenvironment analysis, the estimate package of R was used to calculate the immune score and stromal score based on the CDKN2A expression level." (PMID 35004697, 2021). "Another two tumor suppressors, SMAD4 and CDKN2A, had 53 mutations in 48 samples and 37 mutations in 35 samples, respectively." (PMID 34368001, 2021).
tumor (continued). "CDKN2A expression was associated with infiltrating lymphocyte (TIL) levels in 22 pancancers, thus suggesting that CDKN2A expression is associated with tumor immunity." (PMID 35004697, 2021). "The tumor markers CDKN2A and KRT7 were the most upregulated genes with fold changes 10.7 and 4.8, respectively, while markers for proliferation (MELK, CDK1, MKI67, CCNB2, BUB1, FOXM1, CDKN3) had fold changes spanning from 2.0–2.7." (PMID 35008799, 2021). "To confirm if the results we observed in bioinformatics analyses successfully translated into clinic, we analyzed the expression of CDKN2A protein by IHC and the methylation by MS-PCR with 62 GC specimens and 62 non-tumor tissues." (PMID 33896386, 2021). "More recently, the relationship between p14/ARF encoded by CDKN2A and tumor microenvironment was evaluated." (PMID 34830817, 2021). "Among the genes included in our prediction model, CDKN2A is most well-known for its role in tumor development." (PMID 34948172, 2021). "Expression of senescence markers, such as p16INK4a, is very low in this tumour type, and this is probably due to the oncogenic driver mutations’ ability to represses the CDKN2A locus." (PMID 33378554, 2021). "Therapeutic targeting of CDKN2A presents a challenge of restoring tumour suppressor activity or inhibiting downstream targets that have been rendered overactive." (PMID 34298667, 2021). "More than 50% GBM patients had CDKN2A deletion, and CDKN2A deletion was a bad prognosis across different tumor types." (PMID 33959491, 2021). "Cyclin-dependent kinase inhibitor 2A (CDKN2A) is a known tumor suppressor gene that inhibits cell growth and inhibits tumors." (PMID 34887768, 2021). "Increased expression of p16 (encoded by CDKN2A gene) occurs following E7-mediated phospho-RB1 inactivation, allowing p16-expressing tumor cells to bypass cell cycle arrest." (PMID 35126105, 2021). "CDKN2A expression levels between normal tissues and tumor samples were compared using the TCGA data." (PMID 35004299, 2021). "What’s more, Similar to the results of GEO database, CDKN2A was highly expressed in tumor tissues and lowly expressed in normal tissues in TCGA database." (PMID 34405225, 2021). "The tumour suppressor CDKN2A was identified as the second most commonly altered gene in HNSCC in TCGA." (PMID 34298667, 2021). "In the present study, we systematically analyzed the expression of CDKN2A (mainly mRNA) in tumor tissues of HCC patients in TCGA and GEO databases." (PMID 34405225, 2021).
tumor (continued). "Univariate cox regression suggested that CDKN2A expression (HR = 2.034, 95% CI: 1.129–4.328, P=0.043) and tumor stage (HR = 4.890, 95% CI: 2.017–8.738, P<0.001) were related to OS." (PMID 34405225, 2021). "CDKN2A, known as the cycle-dependent kinase inhibitor gene, belongs to the cycle-dependent kinase inhibitor family and is an important tumor suppressor gene." (PMID 35069688, 2021). "Multivariate cox regression indicated that CDKN2A expression (HR = 2.165, 95% CI: 1.063–4.276, P=0.018) and tumor stage (HR = 5.873, 95% CI: 2.125–10.549, P<0.001) were independent prognostic factors for OS." (PMID 34405225, 2021). "In tumor tissues, the ORs of both TREXes and NCTFs and CDKN2A and CDKN1A increased with the younger age quartile." (PMID 32859952, 2020). "The same study described that Mdm2+/- tumors had a decreased level of p19Arf (Cdkn2a), another tumor suppressor that is reciprocally regulated by N-myc." (PMID 33585251, 2020). "As expected, the levels of protein expression of the three high-risk genes (ITGB4, CDKN2A, and ERO1A) were demonstrably higher in tumour tissues with more intense antibody staining and a greater proportion of stained cells." (PMID 32238163, 2020). "CDKN2A is a gene located at chromosome 9p21, encoding for P16INK4a and P14(ARF) proteins, whose role as a tumor suppressor has been clearly defined in many malignant tumors." (PMID 33154942, 2020). "Conversely, loss of the endogenous CDK4/6 inhibitors (CDKN2A, CDKN2B, CDKN2C, and CDKN2D) or RB-family (RB1, RBL2, and RBL1) are also observed in specific tumor settings, in total the RB-pathway is subject to genetic perturbation in greater than 30% of tumors." (PMID 32242058, 2020). "In high PDIA3 expression samples, frequently amplified genomic peaks were detected in oncogenic drivers, including PDGFRA, EGFR and CDK4; in addition, tumor suppressor genes, such as CDKN2A/CDKN2B and PTEN were observed a deletion peak." (PMID 32687065, 2020). "There are three loci in human chromosome 9p21 as tumor suppressor genes including, CDKN2A (p16INK4a), CDKN2A (p14ARF), and CDKN2B (p15INK4b)." (PMID 33282730, 2020). "We also found 9p- deletion in approximately 50% of GBMs, affecting primarily the 9p21 locus where several tumor suppressor genes are located, including CDKN2A/B and MTAP." (PMID 32093414, 2020). "On the other hand, similar to antecedent studies, the more frequently altered genes were related to cell cycle regulation (ETV6), tumor suppression (CDKN2A/B), apoptosis regulation (BTG1) and others." (PMID 32607130, 2020). "Our analysis identified the prognostic role of high tumor mutation burden with concurrently high CD8 T cell immune marker expression and the aggressive clinical behavior associated with CDKN2A deletion across cancer types." (PMID 33272320, 2020). "Further oncogenic lesions such as CDKN2A p16INK4A loss are required in order to reactivate proliferation, indicating that BRAF V600E mutations require PI3K/Akt dysregulation for the tumor to progress." (PMID 33348922, 2020).